SF3A3 (splicing factor 3a subunit 3)
Description:
Component of the 17S U2 SnRNP complex of the spliceosome, a large ribonucleoprotein complex that removes introns from transcribed pre-mRNAs. The 17S U2 SnRNP complex (1) directly participates in early spliceosome assembly and (2) mediates recognition of the intron branch site during pre-mRNA splicing by promoting the selection of the pre-mRNA branch-site adenosine, the nucleophile for the first step of splicing. Within the 17S U2 SnRNP complex, SF3A3 is part of the SF3A subcomplex that contributes to the assembly of the 17S U2 snRNP, and the subsequent assembly of the pre-spliceosome 'E' complex and the pre-catalytic spliceosome 'A' complex. Involved in pre-mRNA splicing as a component of pre-catalytic spliceosome 'B' complexes.
Synonyms: SAP61; SF3a60; PRP9; PRPF9
Tractability: Small molecule: a structure with a bound ligand is known. PROTAC: ubiquitination databases record sites on it; its protein half-life has been measured.
Target class: Other nuclear protein
Gene: Protein-coding gene on chromosome 1 (37,956,975 to 37,990,517, reverse strand). Ensembl gene ENSG00000183431.
Subcellular location: Nucleus speckle; Nucleus
Subcellular location (Human Protein Atlas): Nuclear speckles; Nucleoplasm
Pathways (Reactome):
Metabolism of RNA: mRNA Polyadenylation; mRNA Splicing - Major Pathway
Chromatin organization: CHD1 and CHD2 subfamily
Disease: Dengue Virus-Host Interactions
Gene Ontology:
Molecular function: protein binding; RNA binding; nucleic acid binding; zinc ion binding
Biological process: mRNA processing; mRNA splicing, via spliceosome; U2-type prespliceosome assembly; mRNA 3'-splice site recognition; RNA splicing, via transesterification reactions; spliceosomal snRNP assembly
Cellular component: catalytic step 2 spliceosome; nuclear speck; nucleus; precatalytic spliceosome; spliceosomal complex; U2 snRNP; U2-type catalytic step 1 spliceosome; U2-type precatalytic spliceosome; U2-type spliceosomal complex; nucleoplasm
Genetic constraint (gnomAD): Loss-of-function variants: 9 observed, 60.46 expected, observed/expected ratio (o/e) 0.15, 90% interval 0.089 to 0.26. The upper end of that interval is the gene's LOEUF score, 0.26, which puts it in group 1 of 6, group 1 being the genes least tolerant of losing a copy. Missense variants: 238 observed, 437.29 expected, observed/expected ratio (o/e) 0.54, 90% interval 0.49 to 0.61. Synonymous variants: 143 observed, 152.12 expected, observed/expected ratio (o/e) 0.94, 90% interval 0.82 to 1.08.
Homologues: Orthologues: chimpanzee SF3A3 (100% identical), dog SF3A3 (99% identical), pig SF3A3 (99% identical), guinea pig SF3A3 (99% identical), rabbit SF3A3 (99% identical), mouse Sf3a3 (99% identical), rat Sf3a3 (99% identical), macaque SF3A3 (98% identical), tropical clawed frog sf3a3 (93% identical), zebrafish sf3a3 (91% identical), Drosophila melanogaster noi (65% identical), Caenorhabditis elegans prp-9 (53% identical). Paralogues in human: SDE2 (15% identical).